LMNTD1 (lamin tail domain containing 1)
Synonyms: IFLTD1; FLJ36004; Pas1c1; LMNARS1
Tractability: No criterion of Open Targets' tractability assessment is met for any kind of drug.
Gene: Protein-coding gene on chromosome 12 (25,409,307 to 25,648,579, reverse strand). Ensembl gene ENSG00000152936.
Subcellular location (Human Protein Atlas): Centrosome; Nucleoplasm
Gene Ontology:
Cellular component: cytoplasm; nuclear envelope
Genetic constraint (gnomAD): Loss-of-function variants: 25 observed, 33.59 expected, observed/expected ratio (o/e) 0.74, 90% interval 0.54 to 1.04. The upper end of that interval is the gene's LOEUF score, 1.04, which puts it in group 4 of 6, group 1 being the genes least tolerant of losing a copy. Missense variants: 406 observed, 428.24 expected, observed/expected ratio (o/e) 0.95, 90% interval 0.87 to 1.03. Synonymous variants: 136 observed, 149.36 expected, observed/expected ratio (o/e) 0.91, 90% interval 0.79 to 1.05.
Homologues: Orthologues: chimpanzee LMNTD1 (97% identical), macaque LMNTD1 (90% identical), rabbit LMNTD1 (65% identical), dog LMNTD1 (64% identical), pig LMNTD1 (63% identical), mouse Lmntd1 (52% identical), rat Lmntd1 (48% identical), Caenorhabditis elegans ifp-1 (6% identical). Paralogues in human: KRT8 (18% identical), KRT73 (17% identical), KRT7 (17% identical), KRT75 (17% identical), KRT84 (17% identical), KRT5 (16% identical), KRT3 (16% identical), KRT74 (16% identical), KRT79 (16% identical), KRT4 (16% identical), KRT82 (16% identical), KRT85 (16% identical), and 56 more.
Diseases named in the same sentence as LMNTD1 in open-access papers:
LMNTD1 is named in the same sentence as 7 diseases in open-access papers, as found by Europe PMC text mining. Sharing a sentence is not in itself a finding about the gene and the disease. The quoted sentences say what the papers report.
lung carcinoma (2 papers, 2021 to 2022). "Insertion mutation in LMNTD1 gene was found in lung cancer patient." (PMID 34143809, 2021). "LMNTD1, also commonly referred to as PAS1C1, is a protein-encoding gene involved in cell population proliferation that is also associated with lung cancer." (PMID 35086473, 2022).
cancer (2 papers, 2021). A tumor composed of atypical neoplastic, often pleomorphic cells that invade other tissues. "Moreover, CREB5 and LMNTD1 genes are associated with cancer." (PMID 34143809, 2021). "For example, cancer-related genes CREB5 and LMNTD1 are associated with BSA, but are not related to the lifestyles used in this study." (PMID 34143809, 2021).
tumor (2 papers, 2022 to 2024). "The first ecDNA was present in the tumor and P14 and a second ecDNA at P0 and P8 that had additional segments e1 containing C12orf77 (chr12:251389380-25148653) and e12 containing LMNTD1 mapping to chr12:25628038-25636598." (PMID 38744814, 2024).
LMNTD1 also shares sentences with these, for which no sentence is quoted: breast carcinoma (2 papers); Cardiovascular Diseases (1); gastric cancer (1); systemic lupus erythematosus (1).